RN7SKP55 (RN7SK pseudogene 55)
Gene: Miscellaneous RNA gene on chromosome 1 (244,943,910 to 244,944,216, forward strand). Ensembl gene ENSG00000201758.
Homologues: Orthologues: chimpanzee 7SK (99% identical). Paralogues in human: 7SK (89% identical), RN7SKP187 (86% identical), RN7SKP48 (85% identical), RN7SKP118 (85% identical), RN7SKP174 (84% identical), RN7SKP227 (82% identical), RN7SKP292 (81% identical), RN7SKP62 (80% identical), RN7SKP76 (80% identical), RN7SKP178 (80% identical), RN7SKP185 (80% identical), RN7SKP104 (75% identical), and 284 more.